CRP (C-reactive protein)
Diseases named in the same sentence as CRP in open-access papers (continued):
Sharing a sentence is not in itself a finding about the gene and the disease.
infection (continued). "Future studies could assess decision making sooner after initial infection and assess inflammatory markers such as C-reactive protein to make sure that the task is performed during the acute phase of sickness." (PMID 40686929, 2025). "Besides infection screening, biomarkers like C-reactive protein and procalcitonin are frequently used in the general population for bacterial infection diagnosis, but with limited use in ACLF patients." (PMID 40150093, 2025). "Given this background, we designed the present study to comprehensively analyze postoperative CRP trends in a cohort of thoracic surgery patients and to determine whether CRP patterns differ by surgical approach or correlate with the occurrence of infections." (PMID 41153812, 2025). "In the clinical management of infections, including nosocomial lower respiratory tract infections (nLRTIs), biomarkers such as C-reactive protein (CRP), procalcitonin (PCT), and soluble triggering receptor expressed on myeloid cells (sTREM-1) play an important role." (PMID 39941194, 2025). "It has been documented that CRP is upregulated by bacterial infections in human being but not in mouse and many mammals, which may affect the infection outcome." (PMID 41214213, 2025). "Interestingly, HRT has also been shown to influence circulating levels of CRP within women, and CRP blood concentrations have been used as markers of infection, cardiovascular disease, and immune responses." (PMID 40254411, 2025). "Research indicates that elevated CRP levels tend to correlate with the severity of the infection." (PMID 41357512, 2025). "In addition, serum C-reactive protein (CRP)-to-albumin ratio (CAR) is also a well-known indicator of infection." (PMID 40978747, 2025). "Conversely, a failure of CRP to decrease by day 3 post-intervention may serve as an early warning for ongoing infection and the need for repeat surgical debridement." (PMID 41556000, 2025). "A declining CRP level after treatment is a positive sign, while continued elevation may indicate ongoing issues, such as incomplete drainage or unresolved infection." (PMID 40142907, 2025). "C-reactive protein (CRP) was mildly elevated at 10 mg/L (reference range: <3 mg/L), which, along with the absence of a clinically evident infection, ruled out a significant infectious cause for decompensation." (PMID 40125203, 2025). "However, although not statistically significant, the sensitivity of 0.8 for preoperative CRP and the absolute difference from the postoperative value should not be underestimated, since it can help in detecting ongoing infections which can lead to further PJI." (PMID 40001448, 2025). "Furthermore, her CRP levels progressively increased, and neutrophil counts remained consistently above average, indicating that the infection was still active." (PMID 41140647, 2025). "Additionally, the patient’s use of high-dose corticosteroids and methotrexate likely blunted systemic signs of infection, such as fever, despite markedly elevated inflammatory markers (CRP and WBC count)." (PMID 40585697, 2025). "The difference in CRP may be related to a higher rate of infection in the major amputation group, while the higher ABI in that group could be attributable to advanced calcification in the lower-extremity arteries." (PMID 40005394, 2025). "C-reactive protein (CRP) is a frequently used marker in the clinical diagnosis of infection." (PMID 40125102, 2025). "Chronic exposure to these agents has been associated with dose-dependent persistently elevated CRP in the absence of infection, as well as an attenuated inflammatory response during actual infection." (PMID 40566045, 2025). "On the other side, CRP rises late in the time course of infection, so single measures early in the course of the illness are not reliable or sufficient; besides, its interpretation can be confounded by other physiological and pathophysiological conditions like the mode of delivery." (PMID 40224545, 2025).
infection (continued). "WBC and CRP are well-established biomarkers for detecting infections." (PMID 41048939, 2025). "C-reactive protein (CRP) is a frequently used marker in the diagnosis of infection." (PMID 40125102, 2025). "As infection control directly affects inflammatory burden and healing, future studies should incorporate standardized wound management protocols and analyze antibiotic response in relation to CRP kinetics." (PMID 41367458, 2025). "We tested to see if the IL-6 and CRP values were sensitive to infection." (PMID 40242671, 2025). "Inflammatory markers are elevated in infection, rheumatoid arthritis and after surgery; on the other hand, the abnormal expressed of fibrinogen and other plasma proteins can increasing the measured markers (such as CRP, ESR and IL-6)." (PMID 41250763, 2025). "Recent clinical investigations have demonstrated that the NLR exhibits superior prognostic accuracy compared with conventional infection biomarkers, including CRP, WBC count, and neutrophil count, in young adult patients presenting with community-acquired pneumonia in emergency department settings." (PMID 40824864, 2025). "Therefore further research investigating the prognostic value of IL-6 and CRP relative to other predictors of postoperative infection is needed to draw final conclusions on the clinical utility of either biomarker." (PMID 40549692, 2025). "Along with elevated body temperature, CRP can serve as a marker of infection." (PMID 40642736, 2025). "Notably, We observed significantly lower renal pelvic pressure, postoperative hemoglobin loss, and inflammatory and infection markers (WBC, CRP, PCT), as well as postoperative complications in the experimental group, leading to a shorter average hospital stay." (PMID 41230511, 2025). "However, due to systemic influences such as other infections or surgical trauma, serum CRP alone has lower specificity for AL detection compared with peritoneal fluid CRP." (PMID 40142907, 2025). "However, as measurement of CRP is a routine part of the assessment of suspected infection in our ED, it would have been unethical to withhold it from the treating physician." (PMID 40579468, 2025). "The medical field has long depended on key biomarkers such as CRP to evaluate infection levels." (PMID 40277527, 2025). "CRP is a widely used serum biomarker for the diagnosis of infection and inflammation." (PMID 41292521, 2025). "Similarly, systemic inflammation or uncontrolled infection was improbable, as the patient’s infection was clinically stable at the time of discharge and inflammatory markers (CRP, procalcitonin)." (PMID 41424752, 2025). "In such cases, it will relieve the clinician and prevent the patient's chemotherapy cycle from being interrupted if it can be established when, under which situations, and to what extent the elevated CRP indicates an infection that would hinder chemotherapy administration." (PMID 40125102, 2025). "As it correlates with lymphocyte count, and NLR and TSH measurement is inexpensive and widely available, TSH could be considered an additional marker of severity of infection with SARS-CoV-2 alongside C-reactive protein (CRP), D-dimers, or procalcitonin." (PMID 41375681, 2025). "PSP may serve as a more sensitive and specific biomarker for sepsis compared to PCT or CRP, with levels increasing rapidly within two hours after infection onset." (PMID 40217689, 2025). "Moreover in our study, the infection biomarkers such CRP, IL-6 and procalcitonin, were balanced between both groups, which suggested that the severity of infection was similar." (PMID 39911872, 2025). "The CRP cutoff value at admission to be considered for predicting infection that would hinder chemotherapy in all patients was ≥6.74 mg/dL with a sensitivity, specificity, positive predictive value, and negative predictive value of 91.3%, 86.6%, 50%, and 98.6%, respectively (p<0.001)." (PMID 40125102, 2025).
infection (continued). "In addition, there were statistically significantly higher inflammatory biomarkers (CRP and WBC) associated with developing early infections, which adds additional meaning to the individuals being screened in the perioperative period." (PMID 40861637, 2025). "Our pragmatic analytical window (12 h before to 48 h after a prescribing decision, or until the next change) aimed to capture early CRP evolution in a dynamic setting, but means observed trajectories are a composite of these influences, ongoing infection severity, and potential testing biases." (PMID 40764898, 2025). "ESR and CRP are more reliable infection indicators than WBC." (PMID 40171003, 2025). "A CRP level ≥145 mg/L was associated with a constellation of more unfavorable clinical indicators (older age, longer ICU stay, higher APACHE II and SOFA scores, more mechanical ventilation, higher AKI and infection rates, and reduced survival) p < 0.05." (PMID 41303205, 2025). "A rapid decrease in CRP after initiation of antibiotic treatment does not exclude malignancy (cancer-associated infections are usually microbiologically responsive)." (PMID 41463208, 2025). "However, the literature also describes cases in which CRP levels remain within the reference range during an infection." (PMID 41301663, 2025). "CRP is an inflammatory marker, which is also elevated in infections." (PMID 40208300, 2025). "Furthermore, changes in white blood cell count alone were insufficient to reflect the infection status, with ESR and CRP proving more effective for monitoring infection and patient recovery stages." (PMID 40248954, 2025). "We excluded subjects with extremely high CRP ( > 10 mg/L) to minimize acute infection bias, but low-grade infections or other chronic diseases might still elevate CRP." (PMID 41159344, 2025). "The distinctive elevation of serum HBP, TNF-α, IL-6, and CRP levels in children with severe adenovirus pneumonia as well as those with poor prognosis underscored the central role of inflammatory pathways in the pathogenesis and prognosis of this infection." (PMID 40963970, 2025). "Similarly, patients with infections showed a distinctly prolonged CRP elevation (often remaining > 100 mg/L at POD5) compared to uncomplicated patients, echoing findings from other surgical cohorts that persistent CRP indicates complication." (PMID 41153812, 2025). "First, due to some missing data in the database, factors including the sites of infection, socioeconomic status and some inflammatory markers such as C-reactive protein couldn’t be evaluated." (PMID 41359607, 2025). "For patients suspected of having an infection, evaluating the full blood count, erythrocyte sedimentation rate, C-reactive protein level and fasting blood sugar level may be helpful." (PMID 40662124, 2025). "In order to be protective against all stages of infection, we hypothesize that CRP binds to two different ligands on pneumococci." (PMID 40740789, 2025). "Thus, while not conclusive on its own, our study’s CRP kinetics align with the broader literature underscoring that “CRP should go down after day 3–4” in normal recovery and that continued elevation is a warning sign of potential infection." (PMID 41153812, 2025). "If the presence of infection is suspected, CRP may need to be assessed on two separate occasions to ensure it is raised." (PMID 40179818, 2025). "In addition, C-reactive protein (CRP) levels increased significantly, and the patient’s body temperature increased, indicating an infection." (PMID 39629232, 2024). "When CRP levels rise, along with the start concentration, it indicates clinical deterioration, which is often accompanied by organ damage and an uncontrolled flare-up that promotes tissue fibrosis months after infection." (PMID 38184750, 2024). "Elevated serum CRP levels often signal infection, inflammation, or tissue damage." (PMID 39685844, 2024).
infection (continued). "In contrast, in persons with high CrAg titer (ie, high fungal burden), we hypothesize that elevated CRP represents a commensurate immune response for a significantly disseminated infection." (PMID 39086467, 2024). "Similarly, Il-6 levels were lower in patients with cancer as compared to patients with infection (t = 2.81, p = 0.007), while Neu and CRP levels were similar to patients with cancer and the normal controls." (PMID 39338437, 2024). "Retrospectively, it is difficult to determine whether CRP dynamics were due to a response to CPI therapy or to an infection or inflammation." (PMID 39001486, 2024). "Moreover, the initial levels of CRP were only moderately elevated, the infection was treated immediately after admission and resolved quickly with clear CRP decline." (PMID 39295933, 2024). "CRP levels above 40 mg/L might represent the natural progression of an infection, particularly depending on when the patient consults at the primary care center." (PMID 39407829, 2024). "Furthermore, serum CRP has been demonstrated to have potential in assisting the diagnosis of infection localization in UTIs, predicting the prognosis of febrile UTIs, and differentiating between inflammatory and non-inflammatory causes of acute scrotum." (PMID 39767771, 2024). "C-reactive protein (CRP) has been used to diagnose surgical infections within the abdomen." (PMID 39525122, 2024). "•C-reactive protein (CRP) is used as biomarker for infection and inflammation." (PMID 38188655, 2024). "CRP rises in response to inflammation, infection, tissue trauma, and various diseases." (PMID 39767688, 2024). "It is also an intriguing possibility that similar CRP centile charts could be used to determine normal post-operative recovery patterns, with deviations potentially indicative of surgical site infection." (PMID 38599549, 2024). "Therefore, it is known that the CRP is a good indicator of acute-phase response in infection, inflammation, and tissue damage." (PMID 39195007, 2024). "Similarly, matching CRP with IL-10 levels, the clinician obtained a higher discriminative ability in the etiology of infection (specificity from 77% to 98%, sensitivity 75%)." (PMID 38254697, 2024). "However, the observed variations in CRP and IL-1α levels during the early phase of infection highlight the dynamic changes in inflammatory responses that occurred during the course of the disease." (PMID 39338474, 2024). "In the end, the mean CRP in blood infection patients is around 0 and it is much lower than the others, indicating its specificity and sensitivity may be lower than PCT." (PMID 38350899, 2024). "In patients with ongoing infections, the average CRP value ranged from 60–75 mg/L." (PMID 39120214, 2024). "In addition, drug fever developed in 19 patients after medication, with some cases occurring after white blood cell counts, CRP, and other infection indicators had returned to normal (n = 5)." (PMID 38623456, 2024). "Therefore, the CRP level on POD 3 has favorable clinical guideline relevance for predicting postoperative infection." (PMID 38504206, 2024). "There was an increase in CRP in patient 3 from baseline (8 mg/L) to week 1 (13 mg/L) which could indicate an incipient infection." (PMID 39588043, 2024). "After being stimulated by tissue damage, infection, or inflammation for 4–6 h, plasma CRP level increases, reaching a peak at 48–72 h, which may continue until the 7th day." (PMID 39411281, 2024). "CRP lacks optimal sensitivity and specificity, IL-6 lacks specificity for hematological malignancies despite its rapid post-infection rise, and PCT may be influenced by coexisting conditions like tumors and thyroid diseases." (PMID 38956649, 2024). "Serum amyloid A (SAA) decreases rapidly postoperatively after its peak on day 3, which enables SAA to represent a great early inflammatory indicator in the investigation of early postoperative infection when the CRP and ESR will still be elevated due to the procedure." (PMID 38592315, 2024).
infection (continued). "CRP is a protein produced by the liver that is an early indicator of infection and inflammation." (PMID 38222708, 2024). "CRP, identified as an acute-phase reactant, is manufactured by the liver and can undergo heightened levels in various circumstances like inflammation, cardiovascular disease, and infection." (PMID 38304653, 2024). "CRP has a high sensitivity for inflammation but little specificity for infection." (PMID 38792824, 2024). "In this study, CRP concentration was utilized to gauge the severity of infection." (PMID 40046178, 2024). "CRP is an acute-phase protein produced by the liver in response to injury and/or infection." (PMID 39857860, 2024). "Thus, understanding standard CRP changes and peaks for each surgical procedure is important for the early diagnosis of postoperative infection." (PMID 39539898, 2024). "Notably, compared to any single indicator alone, a model based on PCT and CRP demonstrated the highest accuracy in predicting infection." (PMID 38956649, 2024). "In contrast, IL-6 and CRP are well-established markers of systemic inflammation and acute-phase responses, serving as sentinel indicators of host defense mechanisms activated in response to infection." (PMID 39066228, 2024). "C-reactive protein (CRP) is considered a more reliable marker of recent infection than ESR." (PMID 39595132, 2024). "The higher CRP levels in the pandemic group may suggest a more severe inflammatory response or a higher burden of infection among patients presenting during the pandemic period." (PMID 38770054, 2024). "In the blood test, high-sensitivity CRP (hs-CRP) was 10.18 mg/dL, which suggests an infection." (PMID 38172867, 2024). "Elevated c-reactive protein (CRP) may be a sign of infection or increased inflammation in these patients and is associated with increased mortality." (PMID 38337563, 2024). "Moreover, In a separate prospective study,the researcher found that NLR normalized faster than CRP and was a better indicator of inflammation and infection in predicting inflammation development after arthroplasty." (PMID 39021876, 2024). "The treatment groups exhibited mild CRP elevations (2–3 mg/L), indicating less severe infection." (PMID 38911027, 2024). "Blood tests revealed a lymphocyte count of 0.19*10^9/L, accompanied by a normal white blood cell (WBC) count, a normal granulocyte count, and CRP of 53.3 mg/L; Blood cultures indicated Staphylococcus hominis, prompting a switch to Teicoplanin and Cefoperazone Sulbactam for infection treatment." (PMID 39776845, 2024). "However, the high performance of these two markers, with AUROCs of 0.93 and 0.94, respectively, should be considered biased, as CRP and procalcitonin were among the leading parameters used by the adjudicators to determine the infection status of the patients." (PMID 38755564, 2024). "Notably, EXTEM MCF was found to have a higher diagnostic accuracy than CRP (p = 0.006) and ESR (p = 0.019), and a higher diagnostic accuracy than D-dimer (p = 0.002) for these infections." (PMID 39203582, 2024). "CRP is synthesized mainly in liver cells, there is growing evidence that CRP plays an important role in inflammatory processes and host response to infection, including the complement pathway, apoptosis, and the production of cytokines, particularly interleukin-6 (IL-6) and tumor necrosis factor-α." (PMID 39720727, 2024). "The objective of this study was to evaluate the clinical performance of serum calprotectin in identifying bacterial infection in febrile infants presenting to an emergency department (ED) relative to other common biomarkers of infection (e.g., C-reactive protein, procalcitonin, and WBC count)." (PMID 38786153, 2024). "Interestingly, and in line with findings from experimentally induced infections, CRP was the only APP where a larger response was apparent in bacterial disease (71-fold increase), compared to viral (9 and 26-fold increase) and inflammation (38-fold)." (PMID 39237955, 2024).